CKAP2 (cytoskeleton associated protein 2)
Diseases named in the same sentence as CKAP2 in open-access papers (continued):
Sharing a sentence is not in itself a finding about the gene and the disease.
ischemic stroke (2 papers, 2025). A stroke disorder caused by obstruction of blood flow to the brain, due to thrombotic (local blood clot formation) or embolic (due to a blood clot or other material traveling from another site) event. "In ischemic stroke, we found that MPO, CALCRL, PPP5C, KTN1-AS1, CCR1, CTB-50L17.9, CCR9, ZNF362, ZIK1, ELP5, CKAP2, NUP88, and SEC16A show risk effects (OR > 1)." (PMID 40624693, 2025).
prostate carcinoma (2 papers, 2012 to 2017). A carcinoma that arises from epithelial cells of the prostate gland. "In addition, in prostate cancer, CKAP2, LASP1, BIRC5, WASF1, ASAP1 and RUNX2 mRNAs were recently identified as new miR-203 targets, suggesting that miR-203 could be a new prognostic marker and a therapeutic target in metastasis of prostate cancer." (PMID 23285092, 2012).
Stroke (2 papers, 2022 to 2024). Sudden impairment of blood flow to a part of the brain due to occlusion or rupture of an artery to the brain. "Wu conducted Mendelian randomization analysis to explore genes associated with stroke in the blood, including CKAP2." (PMID 39009943, 2024). "In blood, we identified 5 genes (MMP12, SCARF1, ABO, F11, and CKAP2) that had causal relationships with stroke and stroke subtypes." (PMID 35449099, 2022). "It is worth investigating whether there is a relationship between the impact of POAF on stroke incidence and the presence of the CKAP2 gene." (PMID 39009943, 2024). "Furthermore, 5 different genes (MMP12, ABO, SCARF1, F11, and CKAP2) were discovered in blood, which indicated two distinct pathogenesis for stroke in brain and blood." (PMID 35449099, 2022).
bone metastasis (1 paper, 2025). Transfer of a neoplasm from its primary site to bones. "The LUAD bone metastasis patients were accompanied by decreased levels of CKAP2 autoantibody, however, the bioinformatic analysis revealed that CKAP2 was correlated with poorer clinical outcomes in NSCLC, indicating that CKAP2 autoantibody may have positive functions in confronting tumors." (PMID 39949782, 2025).
gallbladder carcinoma (1 paper, 2023). "Gene expression heat map showed that KNTC1, MCM2, CKAP2, RACGAP1, CCNB1 were highly expressed in gallbladder carcinoma samples." (PMID 37480569, 2023). "We found that five core genes (KNTC1, MCM2, CKAP2, RACGAP1, CCNB1) were highly expressed in gallbladder carcinoma samples and low in normal samples." (PMID 37480569, 2023).
invasive breast carcinoma (1 paper, 2022). A carcinoma that infiltrates the breast parenchyma. "The pan-cancer analysis of CKAP2 expression showed that it was upregulated in several different tumor types including invasive breast carcinoma." (PMID 35954424, 2022).
lymph node metastasis (1 paper, 2017). "We identified three prognostic factors, including FIGO stage, Lymph node metastasis and CKAP2 expression, can served as independent prognostic factors for poor overall survival." (PMID 28522860, 2017). "The increased CKAP2 expression was significantly correlated with age, FIGO stage, lymph node metastasis, recurrence and tumor size." (PMID 28522860, 2017). "The results showed that increased CKAP2 expression was significantly correlated with age, FIGO stage, lymph node metastasis, recurrence and tumor size, but not other clinical characteristics." (PMID 28522860, 2017).
osteoarthritis (1 paper, 2025). A noninflammatory degenerative joint disease occurring chiefly in older persons, characterized by degeneration of the articular cartilage, hypertrophy of bone at the margins and changes in the synovial membrane. "qRT-PCR, western blot, and IHC demonstrated CKAP2 expression was higher in RA synovial tissue compared to osteoarthritis (OA) samples." (PMID 40636121, 2025).
ovarian adenocarcinoma (1 paper, 2022). An adenocarcinoma that arises from the ovary. "Zhang and Zhao showed that inhibition of CKAP2 by siRNA led to inhibition of migration in ovarian adenocarcinoma cells." (PMID 35954424, 2022).
prostate adenocarcinoma (1 paper, 2022). "The results show that while prostate adenocarcinoma presented the highest percentage of mutations in CKAP2 (in approximately 8% of patients), approximately 2.2% of the patients with invasive BC presented mutations in CKAP2." (PMID 35954424, 2022).
cancer (23 papers, 2011 to 2025). A tumor composed of atypical neoplastic, often pleomorphic cells that invade other tissues. "Upregulation of CKAP2 (Cytoskeleton-associated protein 2) has been shown to directly stimulate cell proliferation in multiple cancer types." (PMID 41246267, 2025). "CKAP2 is a microtubule-associated protein overexpressed in various human cancers and promoting cancer proliferation and tumorigenesis." (PMID 35853854, 2022). "Hence, cells may be susceptible to increased levels of CKAP2 as they have been observed in several types of cancer." (PMID 35029146, 2022). "In such case, HIF-1α-induced transcription of CKAP2 would add a further layer of control to fine-tune the expression of CKAP2 in cancer." (PMID 35853854, 2022). "We next explored CKAP2 gene expression in BC using publicly available databases and cancer repositories." (PMID 35954424, 2022). "The pan-cancer analysis indicated 104 alterations in CKAP2 protein observed in patient samples and localized throughout the protein." (PMID 35954424, 2022). "Taken together, all these studies show the important role of CKAP2 in the progression of different cancers." (PMID 35954424, 2022). "Two independent databases (ONCOMINE—which contained 715 cancer-related microarray datasets—and TIMER—which is based on the TCGA database) were used to evaluate the expression level of CKAP2 across multiple cancers." (PMID 35954424, 2022). "We report widespread and consistent changes in alternative splicing of cancer-associated genes including CENPE, ESCO2, CKAP2, MELK, ASPH and CD164 in both HeLa and PC3 cells." (PMID 33846420, 2021). "The CKAP2 has been shown to be upregulated in many cancer tissues and cell lines, suggesting an important role of CKAP2 in the highly proliferative trait of cancers." (PMID 28522860, 2017). "Immunohistochemical staining of normal gastric tissues adjacent to cancer cells revealed few chromatin CKAP2-positive cells and a low CPCC." (PMID 26542785, 2015). "Prior research has highlighted the predominant role of CKAP2 in multiple cancer types." (PMID 40004022, 2025). "Similarly, other proteins that are enriched at the G2/M phases of the cell cycle, including CKAP2 and Ki‐67, have been shown to have prognostic values in human cancer." (PMID 39073037, 2024). "Previously, we and others reported that CKAP2 is a regulator of mitotic spindle assembly and essential for proper chromosome segregation, and serves as a useful prognostic marker in human cancer." (PMID 39073037, 2024). "Interestingly, the relative differences in CKAP2L and CKAP2 protein levels between cell lines were almost identical, suggesting that the expression of two paralogues is likely to be co‐regulated in cancer cells." (PMID 39073037, 2024). "Furthermore, it has been suggested by work on molecular mechanisms that the proliferation and motility of cancer cells are usually controlled by various CKAP2-mediated signaling pathways." (PMID 36699449, 2022). "Upregulation of a potent growth factor like CKAP2 as observed in many cancers could therefore be directly responsible for CIN, and subsequently for aneuploidy, and malignancies." (PMID 35029146, 2022). "The pan-cancer analysis showed that the level of mRNA correlated with copy number alterations, with the average expression for amplification and deep deletion presenting the highest and lowest levels of CKAP2, respectively." (PMID 35954424, 2022). "Overexpression of CKAP2 promotes cancer formation and correlates with severity of the disease." (PMID 35029146, 2022). "Second, are there any cancer-related targets other than CKAP2 co-regulated by DLEU1 and HIF-1α?" (PMID 35853854, 2022). "The finding in a 1N patient of duplicated CKAP2, THSD1, and VPS36 genes in 13q14.3 is very interesting because CKAP2 is responsible for spindle bipolarity and chromosome stability and may represent a new factor contributing to eye tissue cancer development." (PMID 32577795, 2020).
cancer (continued). "The difference between two markers may be related to the lower background expression of CKAP2 in cancer cells." (PMID 28771517, 2017). "As cancer cells lose the ability to stop at G1 and divide continuously, they always express CKAP2." (PMID 28522860, 2017). "Importantly, these results are in agreement with CKAP2 studies from other types of cancer." (PMID 35954424, 2022). "Consequently, CKAP2 is a marker for the diagnosis and prognosis of several types of cancer." (PMID 35029146, 2022). "The role of CKAP2 expression and BC immunity was investigated using the TIMER2.0 database, which compiles the expression levels of tumor-infiltrating immune cells (TIICs) from TCGA cancers." (PMID 35954424, 2022). "In contrast, the removal of CKAP2 does not seem to be significantly affected even in cancer cells." (PMID 28771517, 2017).
tumor (16 papers, 2011 to 2025). "Zinc finger CCCH-type containing 13 (ZC3H13) is a highly expressed oncogenic m6A writer that modulates centromere protein K (CENPK) and cytoskeleton-associated protein 2 (CKAP2) expression to promote malignant properties, tumour stemness and chemoresistance in CC patients (Refs 45, 46)." (PMID 39377535, 2024). "Many other models were designed by introducing appropriate biomarkers such as serum AFP, HBsAg, cytoskeleton-associated protein 2, plasma fibrinogen which showed improved prognostic power for tumor recurrence and provided a wider perspective to consider for RR indication." (PMID 28968990, 2017). "The subcutaneous tumor formation assay in nude mice showed that CKAP2 silencing significantly reduced the size of mouse tumors, as well as tumor volume and tumor weight (p < 0.01)." (PMID 39403723, 2024). "Meanwhile, HE staining of mice lung tissues revealed the reduction in tumor nodules after CKAP2 downregulation." (PMID 39403723, 2024). "Thus, we speculated that tumor progression caused by overexpression of CKAP2 is related to TFDP1." (PMID 39403723, 2024). "Through IVIS, we found that CKAP2 downregulation resulted in the decrease of luciferase-labeled tumor cells in mice, suggesting the inhibitory effect on tumor lung metastasis in vivo." (PMID 39403723, 2024). "Analysis of the CKAP2 protein levels in BC was performed using UALCAN based on the Clinical Proteomic Tumor Analysis Consortium (CPTAC) database." (PMID 35954424, 2022). "Previous studies suggested that the activation of FAK/ERK or JAK2/STAT3 signaling mediated the pro-tumor activities of CKAP2." (PMID 35853854, 2022). "In this context, we used the spheroid culture system to evaluate aspects of tumor formation upon CKAP2 knockdown." (PMID 35954424, 2022). "By activating ERK and STAT3 signaling, CKAP2 essentially mediated the pro-tumor activities of DLEU1." (PMID 35853854, 2022). "The profiles of DARS-AS1 and Cytoskeleton associated protein 2 (CKAP2) in 50 HCC tissues and non-tumor tissues were examined by real-time quantitative polymerase chain reaction (RT-qPCR)." (PMID 34596006, 2021). "The results demonstrated that CKAP2 was overexpressed in HCC tissues (vs. that in non-tumor tissues)." (PMID 34596006, 2021). "Altogether we would consider aberrations in SNX14, SYNCRIP, CBR3-AS1, and CKAP2 as putatively responsible for tumor development or being at least an important passenger aberration in the respective 1N patients." (PMID 32577795, 2020). "Moreover, CKAP2 promoted the proliferation of HUVECs and angiogenesis via affecting the tumor microenvironment (TME)." (PMID 39403723, 2024). "We analyzed the experimental results of IHC and observed that the positive staining (brown area) of Ki-67, CKAP2, CD163, and CD31 was reduced after CKAP2 knockdown in the tumor tissues of mice, showing the inhibitory effects of CKAP2 knockdown on proliferation and angiogenesis of tumor cells." (PMID 39403723, 2024). "Moreover, we constructed a nude mouse model of CRC and found that silencing of CKAP2 suppressed metastasis and tumor growth in nude mice." (PMID 39403723, 2024). "In addition, we also found that CKAP2 promoted the angiogenesis and proliferation of HUVECs by influencing the tumor microenvironment." (PMID 39403723, 2024). "In vivo silencing of CKAP2 repressed tumor growth and metastasis." (PMID 39403723, 2024). "Importantly, the overexpression (at transcriptional level) of CKAP2 was also confirmed in paired tumor and adjacent normal tissue, as evaluated using TNMplot." (PMID 35954424, 2022). "We found that CKAP2 expression presented weak but significant positive correlations with infiltrating levels of B cells, CD8+ T cells, CD4+ T cells, macrophages, neutrophils, and dendritic cells, indicating a potential function of CKAP2 in regulating the tumor immunology of BC." (PMID 35954424, 2022).
tumor (continued). "Here, we unveiled that CKAP2 was up-regulated in HCC (vs. non-tumor tissues), suggesting that CKAP2 might be involved in HCC progression." (PMID 34596006, 2021). "CKAP2 has been found to exert an essential role in tumor progression." (PMID 34596006, 2021). "Western blotting was used to analyze CKAP2 protein expression in resected tumor tissues." (PMID 28522860, 2017). "Among them, the expression of TIPRAP, WSCD1, TCP11L2, DPP4, CAB39 and PDPK1 were down-regulated, while PARP1, DEPDC1B, CKAP2, ORMDL2, MRPL44, POLD4 and TMEM187 were increased in tumor group." (PMID 39949782, 2025). "CKAP2 endorses the proliferation and metastasis of CRC via moving macrophage differentiation in the tumor microenvironment." (PMID 39403723, 2024). "Immune infiltration analysis revealed the relationship between CKAP2 and tumor immune microenvironment, while the Comparative Toxicology Genome Database (CTD) identified a small molecule compound that may target CKAP2." (PMID 40004022, 2025). "Functionally, both CKAP2 and HIF-1α at least partially mediated the pro-tumor activities of DLEU1." (PMID 35853854, 2022). "miR-3200-5p exerted tumor-suppressive effects in HCC and inactivated CKAP2 and FAK-ERK pathway." (PMID 34596006, 2021).
infection (3 papers, 2017 to 2021). The state of being infected such as from the introduction of a foreign agent such as serum, vaccine, antigenic substance or organism. "Real-time PCR and western blotting analysis of CKAP2 levels revealed that CKAP2 expression was decreased by 94.8 ± 1.2% and 77.7 ± 1.5% in HeLa cells and 97.5 ± 3.9% and 75.4 ± 1.2% in C-33A cells respectively following infection with pLKO.1-EGFP-CKAP2 shRNA-1 compared with control." (PMID 28522860, 2017). "Further exploration of the mechanisms involved in CKAP2 was done by examining the effect of CKAP2 overexpression on cell motility after infection with pLVX-Puro-CKAP2 or empty vector in the presence of FAK inhibitor PF-562271 or ERK2 inhibitor VX-11e in SiHa cells." (PMID 28522860, 2017). "We found collectively among SP-A variants several genes such as AKT1, BTK, CCL9, PPARG, and RELA to exhibit higher expression in females, whereas, CFLAR, C1QC, LSP1, CKAP2, KAT2B, TACC2, and RCC2 exhibited higher expression in males after infection." (PMID 32670284, 2020). "However, in response to infection, male mice exhibited higher expression levels of CFLAR, and FKBP5 (KO, 1A3), AKT1, and CCL9 (1A3, 6A2), C1QC (6A2), LSP1 (1A3, 6A2, and 6A4), CKAP2, and KAT2B (KO), TACC2 (1A0), RCC2 (1A3, 6A2), PPARG (1A3, 6A4), and ERP44 (6A2) compared to females." (PMID 32670284, 2020).
immune dysfunction (1 paper, 2025). "In addition, our study found that the low-expression group of CKAP2 has higher dysfunction, which indicated that the CKAP2 low-expression group had immune dysfunction." (PMID 40004022, 2025). "Our results found that the low CKAP2 expression group displayed higher levels of immune dysfunction, whereas no significant changes were observed in terms of Exclusion, microsatellite instability (MSI), and TIDE scores." (PMID 40004022, 2025).
CKAP2 also shares sentences with these, for which no sentence is quoted: triple-negative breast carcinoma (3 papers); anxiety disorder (2); liver cancer (2); lymphoid cancer (2); Adult-onset autosomal dominant leukodystrophy (1); Anxiety (1); demyelinating disease (1); diffuse large B-cell lymphoma (1); Down syndrome (1); esophageal cancer (1); glioblastoma multiforme (1); ischemia (1); Laron syndrome (1); lung carcinoma (1); microcephaly (1); neuroblastoma (1); neurodegenerative disease (1); Nijmegen breakage syndrome (1); pancreatic cancer (1); progeria (1); rheumatoid arthritis (1); Salmonella Infections (1); squamous cell carcinoma (1); stomach cancer (1).